BECN1 (beclin 1)
Diseases named in the same sentence as BECN1 in open-access papers (continued):
Sharing a sentence is not in itself a finding about the gene and the disease.
diabetes (continued). "However, at 22 weeks post diabetes, glomerular Atg5 and Becn1 were regulated differently indicating another mode of regulation for these genes." (PMID 29725042, 2018). "In addition, Bay11‐7082 suppressed nuclear translocation of p65 and alleviated diabetes‐induced up‐regulation of beclin‐1, LC3‐II and p62." (PMID 28643395, 2017). "Furthermore, the diabetes‐induced increases in nuclear translocation of p65 and beclin‐1 expression were inhibited by catalase overexpression." (PMID 28643395, 2017). "In the other hand, upregulation of beclin 1 and enhanced immunoreactivity for LC3-II in the OPL were found in rats with diabetes caused by STZ which may be attributed to the regulation of autophagy in diabetic animals and may differ based on disease development and time periods studied." (PMID 38540165, 2024). "Examination of the precise underlying mechanisms of vitamin D in STZ‐induced T1DM mouse model and mouse insulinoma 6 (MIN6) β cells revealed that vitamin D increases the expression of LC3 and Beclin 1, autophagic signaling factors that may influence the promotion and development of diabetes." (PMID 33041786, 2020). "In addition, high‐glucose‐induced activation of autophagic flux and apoptosis were largely attenuated by p65 siRNA, suggesting that catalase ameliorates diabetes‐induced autophagy, at least in part by increasing the activity of the NF‐κB pathway and p65‐mediated transcription of BECN1." (PMID 28643395, 2017). "Utilizing PPI topology analysis, mTOR, Parkin, AKT, Beclin-1, P62, LC3A, Pink-1, and PI3K were established as key targets for diabetes treatment." (PMID 39211336, 2024). "In detail, STZ-induced diabetes remarkably reduced the expression of ATG-1, ATG-5, Beclin-1, and LAMP-2." (PMID 36841820, 2023). "We found slight increase in Beclin-1 and the ratio of LC3B-II-to-LC3B-I at weeks 1, 4, and 8 following induction of diabetes compared with the controls." (PMID 30190527, 2018). "Notably, the changes in the p‐mTOR, P62, Beclin‐1, and LC3‐II/LC3‐I ratio were more obvious in surgery‐treated rats with diabetes than in surgery‐treated rats." (PMID 34784444, 2022). "We examined changes in beclin-1 and LC3B-II before and after induction of diabetes and glaucoma." (PMID 30190527, 2018). "Autophagy proteins such as P62, Beclin-1, and LC3 (which are required for autophagosome biogenesis/maturation) regulate selective autophagy, cell survival, cell death, oxidative stress, DNA repair, and inflammation and play important roles in several diseases, such as diabetes and obesity." (PMID 35554836, 2022). "Notably, recent studies had shown that glycyrrhizic acid might improve diabetes-induced sublingual gland damage by regulating oxidative stress, autophagy (including LC3B, Beclin-1, P62/SQTM1 targets), and angiogenesis, so as to restore the homeostasis of oral environment." (PMID 38505420, 2024). "The results provide further support for the role of PTEN, BECN1, FGF21, Klotho, and CTGF in development albuminuric and non-albuminuric CKD in diabetes." (PMID 38540101, 2024). "In the baseline condition (without diabetes and hypertrophy), our results showed that EDL muscle exhibited greater autophagy, as indicated by the upregulation of phospho‐ULK1, Beclin‐1, and p62 proteins." (PMID 37470707, 2023). "The chronic lesion tissues from diabetic mice as well as patients with or without diabetes, typical impaired wound healing models, also appeared to be in an increased level of autophagy accompanying with raised LC3 and beclin-1 proteins." (PMID 27805071, 2016). "The results provide further support for the role of PTEN, BECN1, FGF21, Klotho, and CTGF in the pathogenesis of diabetic kidney disease, and highlight the differences in the molecular pathways of albuminuric and non-albuminuric CKD in diabetes." (PMID 38540101, 2024).
osteosarcoma (39 papers, 2015 to 2025). A usually aggressive malignant bone-forming mesenchymal neoplasm, predominantly affecting adolescents and young adults. "In conclusion, these results suggested that the expression of Siglec-15 and Beclin-1 was associated with pulmonary metastasis in osteosarcoma patients." (PMID 35842729, 2022). "The chemo-photodynamic therapy with this nanoassembly was efficient against osteosarcoma xenografts in vivo and caused ROS-mediated increase in beclin-1 expression and autophagic flux in osteosarcoma cells in vitro." (PMID 34439299, 2021). "Our data clearly showed that Beclin-1 depletion resulted in reduced migration of osteosarcoma cells by suppressing EMT, and the increased migration caused by Beclin-1 overexpression could be reversed by Siglec-15 silencing." (PMID 35842729, 2022). "Indeed, ULK1 knockdown increases apoptosis and sensitizes lung cancer cells to cisplatin Beclin 1 overexpression favored the resistance to gemcitabine-induced apoptosis in osteosarcoma cells; while its downregulation was associated with brain cancer, breast carcinoma, and prostatic carcinoma." (PMID 33014767, 2020). "Overall, our results showed that DNA‐PKcs interact with Beclin‐1, thereby enhancing the autophagy response and ultimately leading to anlotinib resistance in osteosarcoma." (PMID 39924638, 2025). "Chemotherapeutic agents, such as cisplatin (DDP), doxorubicin, and methotrexate, have been shown to upregulate Beclin‐1 expression in osteosarcoma cells, whereas Beclin‐1 knockdown suppresses osteosarcoma cell proliferation, metastasis, and invasion." (PMID 40883962, 2025). "Subsequent investigations into the molecular dynamics of autophagy within osteosarcoma have pinpointed critical regulatory elements, notably Beclin-1 and LC3." (PMID 39655055, 2024). "Second, we further examined the expression of Siglec-15 and Beclin-1 in paired primary osteosarcoma samples and corresponding pulmonary metastases (n = 21 pairs)." (PMID 35842729, 2022). "Both knockout and overexpression of Beclin-1 were used for osteosarcoma cells to verify the role of Siglec-15-induced autophagy in metastasis." (PMID 35842729, 2022). "The expression levels of Siglec-15 and Beclin-1 were detected in osteosarcoma tissues using immunohistochemistry (IHC)." (PMID 35842729, 2022). "Both Siglec-15 and Beclin-1 were highly expressed in the osteosarcoma group presenting with lung metastasis compared to the group without lung metastasis." (PMID 35842729, 2022). "Siglec-15 and Beclin-1 expression was evaluated both in lung metastases and in patients who presented with pulmonary metastasis of osteosarcoma." (PMID 35842729, 2022). "To confirm the role of Siglec-15-induced autophagy in osteosarcoma cell metastasis, we knocked down Beclin-1, a crucial element for the autophagy process, in KHOS cells by siRNA." (PMID 35842729, 2022). "In this study, both Siglec-15 and Beclin-1 expression were detected in primary and metastatic osteosarcoma lesions." (PMID 35842729, 2022). "In our study, we demonstrated that both Siglec-15 and Beclin-1 expression was evaluated in lung metastases compared with paired primary osteosarcoma specimens using IHC." (PMID 35842729, 2022). "The results showed that doxycycline-induced Notch1 increased the levels of LC3B-II and Beclin-1 in osteosarcoma cells in a time-dependent manner." (PMID 34495871, 2021). "MiR-30a-5p downregulation contributes to the chemoresistance of osteosarcoma cells by activating Beclin-1-mediated autophagy." (PMID 31771604, 2019). "Reduced miR-30a expression activated Beclin-1-dependent autophagy, which influenced drug resistance in osteosarcoma cells to DOX." (PMID 28978183, 2017).
osteosarcoma (continued). "Chemotherapy-induced HMGB1 expression in osteosarcoma cells promoted autophagy through controlling the formation of the Beclin 1-phosphatidylinositol 3-kinase class 3 (PI3KC3) complex to inhibit apoptosis and increase drug resistance." (PMID 25622595, 2015). "Additionally, we observed that DNA‐PKcs contribute to anlotinib resistance in osteosarcoma cells by interacting directly with Beclin‐1 and inhibiting its ubiquitination." (PMID 39924638, 2025). "Herein, we found that both Siglec-15 silencing and Beclin-1 depletion could decrease RhoA activation and lessen the formation of lamellipodial protrusions in the submembranous area in osteosarcoma cells." (PMID 35842729, 2022). "IHC experiments were conducted to investigate Siglec-15 and Beclin-1 expression in osteosarcoma." (PMID 35842729, 2022). "First, the Siglec-15 and Beclin-1 proteins were detected in primary osteosarcoma specimens (n = 52), and the primary osteosarcoma specimens were divided into two groups according to the presence or absence of pulmonary metastasis at the time of surgical resection (evidenced by medical imaging)." (PMID 35842729, 2022). "Activation of Wnt/β-catenin signaling pathways play essential roles and may rescue chemotherapy drug resistance by targeting Beclin 1 in osteosarcoma cells." (PMID 33472642, 2021). "In addition, decreased LC3-II and beclin-1 levels accompanied by increased p62 expression were observed by WB after PD-L2 knockdown in osteosarcoma cells." (PMID 30886151, 2019). "In addition, overexpression of TSSC3 in osteosarcoma cell lines increased BECN1 and ATG5 mRNA levels." (PMID 30092789, 2018). "Studies have reported elevated expression of the autophagy-related proteins Atg-5, Beclin 1, and LC3-II, along with increased autophagic flux in Neuro-2a and human osteosarcoma cell lines, respectively." (PMID 38267572, 2024). "In the present study, we demonstrated that SpiA promoted autophagy processes through Beclin-1, p62, and the conversion of LC3I to LC3II, and autophagic vacuoles in human osteosarcoma cells." (PMID 39456416, 2024). "In addition, the autophagy induced by Siglec-15 could promote EMT and affect cytoskeletal rearrangement through the effect of these two pathways, and Siglec-15-induced autophagy promoted the invasion and metastasis of human osteosarcoma cells via the Beclin-1/ATG14 pathways." (PMID 35842729, 2022). "Ultimately, all these findings, through both genetic inhibition and overexpression of autophagy, indicated that Siglec-15-induced autophagy promoted the invasive and migratory ability of human osteosarcoma cells by targeting the EMT and Beclin-1/ATG14 pathway." (PMID 35842729, 2022). "In the next set of experiments, effects of sirtuin family members on autophagy markers beclin-1 and LC3 were followed in U2OS human osteosarcoma cells, Mero-14 and REN mesothelioma cells." (PMID 31608237, 2019). "Furthermore, inhibition of autophagy through Beclin‐1 and LC3B knockdown reduces both metastasis and chemoresistance in osteosarcoma cells." (PMID 40883962, 2025). "Remarkably, co‐IP revealed that Beclin‐1 was successfully precipitated by the DNA‐PKcs antibody, whereas DNA‐PKcs was pulled down by the anti‐Beclin‐1 antibody in MG63 cells and human osteosarcoma tissues, providing evidence for the interplay between DNA‐PKcs and Beclin‐1." (PMID 39924638, 2025). "Additionally, IF staining demonstrated the co‐localisation of DNA‐PKcs with Beclin‐1 in MG63 cells, U‐2 OS cells, as well as in human osteosarcoma tissues." (PMID 39924638, 2025). "SIRT1 displayed cell type specific effects as it exerted pro-death activities in osteosarcoma but not in mesothelioma cells possibly attributed to selective modulation of beclin-1 protein levels in U2OS cells." (PMID 31608237, 2019). "TIIA treatment effectively inhibited soft agar colony formation of mock and BECN1 knockdown osteosarcoma cells, but not of SESN2 shRNA cells." (PMID 30258193, 2018).
osteosarcoma (continued). "This was observed in OVC-cMES-103 cells (non-cancer mesenchymal cells) but was not seen in any in cell lines derived from osteosarcoma; instead, beclin-1 expression typically decreased with increasing doxorubicin (lanes 1 vs 4 vs 7)." (PMID 30372478, 2018). "KHOS cells that transfected with BECN1 siRNA presented LC3-II expression decrease after Apatinib settlement when compared with siRNA negative control, showing that the participation of BECN1 triggered autophagy in osteosarcoma cells." (PMID 28837148, 2017). "Similarly, both Siglec-15 and Beclin-1 were also highly expressed in the group with pulmonary metastasis of osteosarcoma compared to the group without lung metastasis." (PMID 35842729, 2022). "The selective regulation on beclin-1 protein levels exerted by resveratrol only in mesothelioma and not in osteosarcoma cells is possibly due to the fact that NAD+/NADH ratio and ROS generation in the two cell types upon resveratrol treatment are regulated by different pathways." (PMID 31608237, 2019). "Additionally, we demonstrated that Siglec-15 silencing reduced the expression of Beclin-1/ATG14, and Siglec-15-related autophagy could promote EMT and affect cytoskeletal rearrangement, through which Siglec-15-induced autophagy participated in the regulation of osteosarcoma cell metastasis." (PMID 35842729, 2022).
leukemia (38 papers, 2011 to 2025). A malignant (clonal) hematologic disorder, involving hematopoietic stem cells and characterized by the presence of primitive or atypical myeloid or lymphoid cells in the bone marrow and the blood. "This intricate relationship between Beclin-1 and oncogenic proteins in leukemia underlines the critical role of autophagy in cancer biology, offering insights into novel therapeutic targets." (PMID 38887520, 2024). "To date, two different short BECN1-splicing variants have been reported, respectively, in leukemia cells and HeLa cells." (PMID 36008963, 2022). "Further research into the mechanism underlying the role of Beclin 1 in leukemia lead to the finding that BCR-ABL binds to Beclin 1 and phosphorylates it at Y233 and Y352." (PMID 33287140, 2020). "Additionally, it induces autophagy, as evidenced by increased levels of LC3‐II and beclin‐1, suggesting a dual mechanism of apoptosis and autophagy underlying its cytotoxic activity in leukemia." (PMID 40927046, 2025). "In fact, Beclin-1 has been implicated in the progression of solid tumors and leukemia." (PMID 24585095, 2014). "The promotion of autophagy by DHRSX involves the downregulation of AKT/mTOR phosphorylation and the upregulation of beclin-1, which are highly related to the antiapoptotic function and chemotherapy resistance of leukemia cells." (PMID 38811988, 2024). "BECN1-β and -γ were found to be co-expressed in the same donor cell line along with the canonical wild-type isoform (BECN1-wt) and with a fourth isoform (here referred to as BECN1-α) already found by another group in leukemia cells." (PMID 36008963, 2022). "Consistently, infection of leukemia cells including K562 cells with adenovirus overexpressing beclin-1 enhanced autophagic activity." (PMID 27070592, 2016). "In other leukemic cell lines, arsenic trioxide did not only induce apoptosis but also induced autophagic cell death in leukemia cell lines via upregulation of Beclin-1." (PMID 21912568, 2012). "Arsenic trioxide was found to induce autophagic cell death in malignant glioma, leukemia and fibrosarcoma cells, and in leukemia this effect was accompanied by up-regulation of beclin-1." (PMID 21299897, 2011). "The ULK1 protein and Beclin-1 protein play a key role in the autophagy process of leukemia." (PMID 38887520, 2024). "More and more studies have shown that Beclin-1-induced autophagy plays a role in leukemia." (PMID 38887520, 2024). "Two shorter isoforms of BECN1 have been found respectively in leukemia and HeLa cells." (PMID 36008963, 2022). "In addition, leukemia stem cells (LSCs) showing resistance to bromodomain and extraterminal domain inhibitors exhibited upregulation of BECN1/Beclin-1 and increased autophagy via activation of the AMPK (p-Thr172)/ULK1 (p-Ser555) pathway." (PMID 35526025, 2022). "In addition to in vitro analysis, tests on the inhibitory function of Beclin 1 in vivo were performed using a leukemia cell-based xenograft animal model." (PMID 34075202, 2021). "Beclin 1-defective leukemia cells were more sensitive to necroptotic stimuli in vitro and in vivo with increased MLKL oligomerization, suggesting that Beclin 1 might be a good target for the treatment of leukemia patients." (PMID 34075202, 2021). "Finally, Beclin 1 depletion was found to promote necroptosis in leukaemia cells and enhance regression of xenografted-tumour upon treatment with Smac mimetics and caspase inhibitors." (PMID 32457484, 2020). "A novel OVV showing Beclin-1 (OVV-BECN1) was examined for its oncolytic effect in leukemia." (PMID 33704184, 2020). "Indeed, in JQ1-resistant leukemia stem cells, BECN1 expression, LC3B-II levels, and global autophagy were increased." (PMID 31861179, 2019). "Indeed, enhanced alternative autophagy was stimulated by 20 μM etoposide, as demonstrated by a further pronounced increase in RAB9A and BECN1 in K562 leukemia cells." (PMID 27091640, 2016).